RNU1-14P (RNA, U1 small nuclear 14, pseudogene)
Synonyms: U1P17; RNU1P7
Gene: Small nuclear RNA gene on chromosome 7 (53,366,058 to 53,366,209, forward strand). Ensembl gene ENSG00000199629.
Homologues: Orthologues: chimpanzee U1 (98% identical), mouse Gm22155 (89% identical), guinea pig U1 (85% identical). Paralogues in human: RNU1-1 (92% identical), RNU1-2 (92% identical), RNU1-27P (92% identical), RNU1-28P (92% identical), RNU1-3 (92% identical), RNU1-4 (92% identical), RNVU1-18 (92% identical), RNVU1-29 (92% identical), RNVU1-31 (92% identical), U1 (92% identical), RNU1-18P (91% identical), RNVU1-28 (91% identical), and 133 more.